KIT (KIT proto-oncogene, receptor tyrosine kinase)
Diseases named in the same sentence as KIT in open-access papers (continued):
Sharing a sentence is not in itself a finding about the gene and the disease.
melanoma (continued). "Mutations in the c-KIT gene, along with BRAF mutations, in part, considered to be involved in the mechanism of development and progression of melanoma, have been identified in mucosal melanoma, which not only implicates BRAF, but also c-KIT, as a promising molecular target." (PMID 25120707, 2014). "By contrast, in most patients, melanoma cells did not express the SCF-R KIT, G-CSF-R, IL-3-R or AC133." (PMID 24489649, 2014). "Unexpectedly, the stem cell factor receptor KIT was only detectable on normal melanocytes but not on melanoma cells." (PMID 24489649, 2014). "In the clinical setting, BRAF mutations are routinely screened but when BRAF mutation is not detected, melanomas should be screened for N-RAS, KIT, and GNAQ mutations." (PMID 24591764, 2014). "The absence of KIT on primary human melanoma cells in most patients was a somehow unexpected finding." (PMID 24489649, 2014). "In fact, neither the freshly isolated primary melanoma cells nor melanoma cells isolated from metastatic tumor cell lesions expressed KIT." (PMID 24489649, 2014). "Melanomas arising in chronically sun-damaged skin, mucosal surfaces, and acral skin were characterized by wild-type BRAF and wild-type NRAS but exhibited alterations in KIT." (PMID 24416617, 2013). "Although the benefit of B-RAF inhibition as monotherapy has been sufficiently confirmed, rapidly occuring secondary resistance mechanisms in tumors will most likely favor combination therapies targeting other genetic “hot spots” in melanoma such as MEK, RAS, and KIT." (PMID 22007305, 2011). "c-KIT aberrations do not seem to typically overlap with mutations such as B-RAF and NRAS even though these are amongst the most common mutations in melanoma." (PMID 21479172, 2011). "KIT, a receptor tyrosine kinase, and EDNRB, a G-protein coupled receptor, are critical regulators in melanocyte development and pigmentation signalling, hair and skin development, and melanoma progression." (PMID 21294715, 2011). "In conclusion, our study supports the finding that KIT mutations presumably activating the tyrosine kinase activity of c-KIT can be found in a subgroup of patients with mucosal melanomas irrespective of the origin of the primary tumour." (PMID 19018266, 2008). "Recent data suggested an increased frequency of KIT aberrations in mucosal melanomas, whereas c-KIT in most types of cutaneous melanomas does not appear to be of pathogenetic importance." (PMID 19018266, 2008). "Furthermore, novel agents like ponatinib, approved by the FDA for CML and Ph + ALL but not yet for melanoma, which targets KIT and angiogenic pathways, have demonstrated potential in overcoming resistance." (PMID 40508177, 2025). "Overall, inhibitor performance in melanoma is driven by molecular genotype and influenced by subtype, with BRAF/MEK inhibitors offering the strongest benefit in BRAF V600–mutant cutaneous disease and KIT inhibitors providing a limited but targeted option for select non-cutaneous subtypes." (PMID 41302945, 2025). "Meningeal melanocytomas and melanomas do not usually harbor HRAS, KRAS, BRAF, or KIT mutations." (PMID 39061148, 2024). "By contrast, high-CSD melanomas do not harbor BRAF V600E mutations but present other mitogen-activated protein kinase (MAPK) pathway mutations, such as BRAF V600K, NRAS G12/G13, or KIT mutations, or inactivation of the negative regulators of Ras, such as NF1 or RASA2." (PMID 38396984, 2024). "Although currently there are no approved KIT inhibitors for melanoma, KIT inhibitor imatinib has shown to provide a durable response to a subset of patients with KIT mutant metastatic melanoma with a complete response lasting for more than 1.5 years in a subset of patients." (PMID 37239381, 2023). "We found KIT extrachromosomal DNA may have contributed to the lack of response to KIT inhibitors of a KIT-driven melanoma." (PMID 36977461, 2023).
melanoma (continued). "Although SCF/c-KIT is an upstream signal for PI3K/AKT activation in melanocyte and melanoma cells 39, 40, whether c-KIT has such a negative feedback loop remains to be demonstrated experimentally." (PMID 37781032, 2023). "In contrast, melanomas from chronically sun-damaged skin or from sites not routinely exposed such as acral or mucosal sites do not typically carry BRAF mutations and would be more associated with NRAS and KIT mutations respectively." (PMID 35712493, 2022). "However, combining KIT and MEK inhibitors may represent a valuable treatment option for patients with KIT-mutant melanoma." (PMID 35234863, 2022). "However, clinical trials that demonstrated efficacy of sorafenib in combination therapy were not specific to melanoma with KIT alterations." (PMID 35954441, 2022). "Two of these four melanomas had mutations in NF1, one in KIT and one in GNA11 (data not shown)." (PMID 36077603, 2022). "Notably, none of the cases were found to harbor SF3B1, NF1, KIT and PDGFRA mutations in cutaneous melanomas, acral melanomas and melanomas of nasal cavity." (PMID 34102999, 2021). "KIT-targeted therapies have not shown satisfactory effect in melanoma to date." (PMID 34889232, 2021). "KIT mutations are primarily associated with acral and mucosal melanoma, and have been reported to show higher prevalence in chronic sun-damaged (CSD) than non-CSD melanomas." (PMID 33648909, 2021). "Non-CSD-associated melanomas encompass acral and mucosal melanomas that usually do not show BRAF, NRAS, or NF1 mutations (triple wild-type), but in a subset may have KIT or SF3B1 mutations." (PMID 34571969, 2021). "However, on the third place on the list of mutant oncogenes is KIT in skin melanoma, initially considered to occur in melanomas of the non-UV sites." (PMID 31848942, 2020). "Until now, none KIT-TKI has received an approval for KIT-mutant melanoma." (PMID 33109256, 2020). "It is worth noting that the regulation of KIT by MITF in melanocytes and melanoma cells remains to be clearly demonstrated, indicating that a tissue specific regulation of KIT by MITF in mast cells might be explained by expression of lineage-restricted cofactors." (PMID 33276788, 2020). "KIT activation triggers a variety of downstream pathways, including MAPK/MEK and PBK/AKT pathways, which may play an important role in the development of melanoma." (PMID 29492238, 2018). "Finally, both SH3BP2 and MITF may also be useful targets, in other malignancies in which KIT is the driven molecule, such as acute myeloid leukemia (AML), mastocytosis, or certain cases of melanoma." (PMID 29885053, 2018). "This may shed some light on the triple‐wild‐type group and those melanomas not amenable to KIT inhibitory treatment." (PMID 28267273, 2017). "We found that the ERK pathway is constitutively activated in Grey horse melanoma tumours and cells in the absence of somatic oncogenic mutations in BRAF, RAS, GNAQ, GNA11 and KIT that are associated with activation of this pathway in the majority of human melanocytic tumours." (PMID 25413220, 2014). "Among other key observations, melanoma cells differ from normal skin melanocytes in EPO-R expression and lack of KIT, suggesting that transformation may be associated with disturbance or deregulation of cytokine receptors." (PMID 24489649, 2014). "First, KIT may induce differentiation rather than proliferation in melanocyte-committed progenitors, so that this pathway has to be bypassed or deleted by the melanoma-initiating oncogenic machinery." (PMID 24489649, 2014).
melanoma (continued). "We found that the ERK pathway is constitutively activated in Grey horse melanoma tumours and cell lines in the absence of somatic activating mutations in BRAF, RAS, GNAQ, GNA11 and KIT genes or alterations in the expression of the main components of the pathway." (PMID 25413220, 2014). "Overexpression of KIT in melanoma was found not to confer sensitivity to imatinib." (PMID 24743024, 2014). "To address whether the general patterns of CpG island methylation discovered above are reflected in frozen tumor tissue samples obtained from malignant melanoma (stages III and IV) patients, we measured CpG island methylation status of upstream regulatory regions of SNORD-10 and c-KIT." (PMID 24129253, 2013). "However, tyrosine kinase inhibitors show little or no activity in melanoma cells harbouring wild-type KIT." (PMID 22281663, 2012). "The KIT gene is wild-type (WT) in melanomas arising from skin without CSD." (PMID 22536370, 2012). "This study did not test for KIT amplifications, which may also represent a melanoma subset sensitive to kinase-directed therapy." (PMID 20372153, 2010). "However, studies investigating the status of the KIT gene in larger, well-characterised groups of patients with mucosal melanomas are lacking." (PMID 19018266, 2008). "Indeed, the expression dynamics of SOX10 and KIT during melanoma progression reveal an intriguing pattern: SOX10 expression gradually increases throughout disease progression, whereas KIT shows biphasic regulation—upregulated in primary melanoma but subsequently downregulated during metastasis." (PMID 40458894, 2025). "Importantly, KIT-mutant melanomas may not be uniformly immunologically “cold,” as some patients have shown responses to PD-1 or CTLA-4 blockade." (PMID 41301010, 2025). "Overall, by affecting the expression levels of both KIT and BCL-2 proteins and, consequently, by impinging on MAPK and PI3K/AKT pathways, as well as on the balance between pro-death and pro-survival factors, our compound may be used to interfere with oncogene expression in melanoma cells." (PMID 31635389, 2019). "Therefore, whatever the mechanism of KIT-negativity in melanoma cells might be, KIT and KIT-dependent signaling apparently is neither critical to melanoma-initiation nor to progression or metastasis formation." (PMID 24489649, 2014). "Due to the detection of the V600E BRAF mutation in this fistula melanoma, it was decided not to look for alterations in genes such as CCND1 or KIT, more frequently mutated in acral and mucosal melanomas, since concomitant mutations in BRAF and in genes such as KIT or CCND1 are extremely rare." (PMID 21827678, 2011). "Furthermore, in agreement with earlier studies we could not show a prognostic relevance of the c-KIT protein expression in mucosal melanomas." (PMID 19018266, 2008). "WGS studies have suggested that TWT melanomas, commonly of the AM subtype, are more likely to have focal amplifications of CCND1, MDM2, KIT, and KRAS, as well as CDK4 and CDK6, than non-TWT melanomas." (PMID 39858514, 2025). "KIT, a tyrosine kinase receptor which activates the RAS and PI3K pathways, is more frequently observed in melanomas originating from non-sun-exposed types." (PMID 40331942, 2025). "Based on data from the present study and others, BRAF-mutant GIST does not respond well to KIT TKIs but does respond well to combination BRAF and MEK inhibition, as is seen in other BRAF-driven cancers, such as melanoma." (PMID 38730662, 2024). "GAB2 CNV gains have also been reported in non-sun-damaged melanoma, including AMs and MUs, and have been reported to be mutually exclusive of BRAF, NRAS, and KIT aberrations." (PMID 33826614, 2021). "While KIT may not represent a reliable primary therapeutic target in melanoma due to it being mutated in a small fraction of lesions, its relevance as a target may be envisaged in the context of acquired drug resistance of BRAF-mutant melanoma treated with targeted therapies." (PMID 31635389, 2019).
melanoma (continued). "Because the pharmacological evidences of GSK414 and KIRA6 were obtained in melanoma cells that do not rely on KIT signaling for survival, we tested the pharmacological usefulness of GSK414 and KIRA6 as KIT inhibitors for therapy." (PMID 30931942, 2019). "Among 253 melanomas, 129 (51.0%) BRAF, 45 (17.8%) NRAS, 6 (2.4%) KIT, 4 (1.6%) GNAQ, 2 (0.8%) GNA11, 2 (0.8%) MAP2K1 and no MAP2K2 gene mutations were detected by the biochip assay." (PMID 28881731, 2017). "In tumors, five genes (KIT, MGMT, MITF, TERT, and TNF) exhibited methylation levels significantly different between tumor groups including acral compared to nonacral melanomas and matched primary lesions and metastases." (PMID 26106605, 2015). "In most patients, melanoma cells exhibited ErbB3/Her3, CD44/Pgp-1, ICAM-1/CD54 and IGF-1-R/CD221, but did not express CD20, ErbB2/Her2, KIT/CD117, AC133/CD133 or MDR-1/CD243." (PMID 24489649, 2014). "Studies done in vitro and in vivo in melanoma cells have shown that exposure of c-KIT positive cells to SCF triggers apoptosis, which does not happen in c-KIT negative cells or in normal melanocytes." (PMID 22839358, 2012). "In melanoma cells with or without BRAFV600E inhibitor resistance, inhibiting the expression of CDK2, CDK4, KIT, and VWF may become a new choice to inhibit the progression of melanoma." (PMID 34582363, 2021). "In human melanoma samples, expression of MYSM1 was increased compared with normal skin melanocytes and nevi and co-localized with melanocyte markers such as Melan-A and c-KIT." (PMID 28978033, 2017). "It is known that elimination of TFAP2A from non-metastatic primary melanoma cells increases their malignancy while re-expression abrogates it, by controlling transcription of genes such as MCAM-MUC18, MMP2, PAR1, VEGF, BCL2, CDKN1A/p21, E-cadherin and KIT." (PMID 25650662, 2015). "The results of our study show that normal melanocytes express huge amounts of KIT (CD117) on their surface, but do not express EPO-R, whereas in most patients, melanoma cells did not express detectable KIT, but expressed the EPO-R in a clearly detectable subpopulation." (PMID 24489649, 2014). "Additionally, lenvatinib’s secondary antitumor effect is its direct melanoma cytotoxicity, which was not VEGFR-2 dependent and alternatively could be due to effects on FGFRs, PDGFRα, KIT, or RET." (PMID 36821392, 2023). "However, an overexpression of KIT and CDK4 has been identified in a subgroup of cutaneous malignant melanomas and would be a mechanism of potential oncogenic transformation of nonmutated BRAF or NRAS melanomas." (PMID 24416617, 2013).
leukemia (242 papers, 2010 to 2026). A malignant (clonal) hematologic disorder, involving hematopoietic stem cells and characterized by the presence of primitive or atypical myeloid or lymphoid cells in the bone marrow and the blood. "The proteasome inhibitor bortezomib (BOR) has shown to modulate the c-KIT-associated apoptosis cascade in leukemia cells by directly inducing c-KIT internalization and lysosome-induced degradation." (PMID 40786504, 2025). "Examples abound, including the impact of KIT mutations and secondary genetic lesions in core-binding factor leukemia, as well as the influence of age on FLT3-ITD mutated leukemia." (PMID 38571944, 2024). "In terms of cellular pathways, these genes are mainly associated with mutations in the interleukin pathway and in the FLT3 and KIT genes (which are also mainly associated with leukaemia)." (PMID 38127054, 2023). "In AML, it has been noted that the KIT mutation is associated with a poor prognosis in primary CBF leukemia." (PMID 35563085, 2022). "In AML, KIT mutation is the most common cooperating mutation in AML1-ETO leukaemia, adversely affecting the disease outcome." (PMID 33833412, 2022). "Due to the high incidence of activating KIT mutations in AML1-ETO leukaemia, KIT signalling is considered a superb target." (PMID 33833412, 2022). "DBF activates the expression of genes encoding the proteins involved in leukemia cell survival, such as KIT, CTNNB1, CCNE1, NFKB1, E2F1, and downregulates the expression of CCND2, CCNA1, and FLT3 genes." (PMID 34564151, 2021). "A promising recent report revealed that inhibition of mutated c-KIT using avapritinib in AML1/ETO-positive leukemia restored sensitivity to PARP inhibition via downregulation of BRCA1/2." (PMID 34331016, 2021). "KIT is a well-established regulator of leukemia cell survival and activating mutations in KIT cooperate with Cbfb-MYH11 during leukemia development." (PMID 30742053, 2019). "In conclusion, we show that in leukemia cells, N822K- and V560G-mutated KIT can initiate growth signals in lipid rafts of the Golgi apparatus." (PMID 31484543, 2019). "With the exception of CSF2RB− IL1RL1− KIT− cells, we found that each sub-population caused leukemia at both the 1,000 and 10,000 cell doses, indicating that each of these sub-populations contains LSCs." (PMID 30742053, 2019). "We also tested dasatinib-DNA Au-NPs with the Kasumi-1 leukemia cell line that harbors an activating KIT mutation and expresses BIRC5 mRNA." (PMID 27203672, 2016). "The incidence of KIT mutations is higher in core-binding factor leukemia, being found in about 7%–46% of cases." (PMID 26239249, 2015). "The presence of KIT mutations in core binding factor leukemia is generally accepted to be associated with a worse prognosis." (PMID 26239249, 2015). "The presence of a KIT mutation in core binding factor leukemia worsens the prognostic category to intermediate." (PMID 26239249, 2015). "Gain of function mutations in c-kit result in constitutive KIT activation and are related to mastocytosis but also other neoplastic transformations including leukaemias, melanoma and others types of cancer." (PMID 22031830, 2011). "Additionally, c‐KIT activating mutations have been shown to confer resistance to PARP inhibitors in AML1–ETO–positive leukaemias." (PMID 40612409, 2025). "As expected, genes associated with AML proliferation (FLT3, KIT), leukemia stem cells (CD34, CD38, and IL1RAP), and candidate genes overexpressed in AML (CD99, CD200, and LAMP2) were downregulated after chemotherapy, consistent with recent scRNA-Seq and immunohistochemistry data." (PMID 36099049, 2022). "Considering that our patients harbored KIT mutations, which could also result in leukemia cell proliferation, we speculate that the activation of KIT mutation signals may be the cause of drug resistance." (PMID 35211416, 2022).